DIS3L2 (DIS3 like 3'-5' exoribonuclease 2)
Description:
3'-5'-exoribonuclease that specifically recognizes RNAs polyuridylated at their 3' end and mediates their degradation. Component of an exosome-independent RNA degradation pathway that mediates degradation of both mRNAs and miRNAs that have been polyuridylated by a terminal uridylyltransferase, such as ZCCHC11/TUT4. Mediates degradation of cytoplasmic mRNAs that have been deadenylated and subsequently uridylated at their 3'. Mediates degradation of uridylated pre-let-7 miRNAs, contributing to the maintenance of embryonic stem (ES) cells. Essential for correct mitosis, and negatively regulates cell proliferation.
Synonyms: hDIS3L2; FAM6A; FLJ36974; MGC42174; PRLMNS
Tractability: PROTAC: ubiquitination databases record sites on it; its protein half-life has been measured.
Target class: Enzyme; Hydrolase
Gene: Protein-coding gene on chromosome 2 (231,961,245 to 232,344,350, forward strand). Ensembl gene ENSG00000144535.
Subcellular location: Cytoplasm; Cytoplasm, P-body
Pathways (Reactome):
Developmental Biology: Z-decay: degradation of maternal mRNAs by zygotically expressed factors
Gene Ontology:
Molecular function: 3'-5'-RNA exonuclease activity; magnesium ion binding; poly(U) RNA binding; protein binding; RNA nuclease activity; RNA binding
Biological process: miRNA catabolic process; mitotic cell cycle; mitotic sister chromatid separation; negative regulation of cell population proliferation; nuclear-transcribed mRNA catabolic process; mRNA catabolic process; polyuridylation-dependent mRNA catabolic process; stem cell population maintenance
Cellular component: cytoplasm; P-body
Genetic constraint (gnomAD): Loss-of-function variants: 33 observed, 94.23 expected, observed/expected ratio (o/e) 0.35, 90% interval 0.26 to 0.47. The upper end of that interval is the gene's LOEUF score, 0.47, which puts it in group 2 of 6, group 1 being the genes least tolerant of losing a copy. Missense variants: 1,016 observed, 1,145.9 expected, observed/expected ratio (o/e) 0.89, 90% interval 0.84 to 0.93. Synonymous variants: 431 observed, 447.27 expected, observed/expected ratio (o/e) 0.96, 90% interval 0.89 to 1.04.
Gene-disease validity (ClinGen):
ClinGen rates the evidence that DIS3L2 causes each of these diseases.
Perlman syndrome (autosomal recessive): Definitive. Perlman syndrome is characterized principally by polyhydramnios, neonatal macrosomia, bilateral renal tumors (hamartomas with or without nephroblastomatosis), hypertrophy of the islets of Langerhans and facial dysmorphism.
Homologues: Orthologues: chimpanzee DIS3L2 (99% identical), macaque DIS3L2 (97% identical), pig DIS3L2 (88% identical), dog DIS3L2 (87% identical), rat Dis3l2 (87% identical), mouse Dis3l2 (86% identical), guinea pig DIS3L2 (84% identical), tropical clawed frog dis3l2 (64% identical), zebrafish dis3l2 (58% identical), Caenorhabditis elegans disl-2 (39% identical), Drosophila melanogaster Dis3l2 (31% identical). Paralogues in human: DIS3L (28% identical), DIS3 (28% identical).
Diseases named in the same sentence as DIS3L2 in open-access papers:
DIS3L2 is named in the same sentence as 34 diseases in open-access papers, as found by Europe PMC text mining. Sharing a sentence is not in itself a finding about the gene and the disease. The quoted sentences say what the papers report.
Perlman syndrome (29 papers, 2012 to 2025). "DIS3-Like 3-prime-5-prime Exoribonuclease 2 (DIS3L2), in which pathogenic variants have been linked to Perlman syndrome (PRLMNS), is an RNA-binding protein with 3′-5′ exoribonuclease activity." (PMID 38894719, 2024). "The deletion of the DIS3L2 gene causes the extremely uncommon congenital overgrowth syndrome, known as Perlman syndrome, which is autosomal recessive." (PMID 38161545, 2023). "DIS3-like exonuclease 2 (DIS3L2) has been reported as a potential reader, its mutation being linked to the Perlman syndrome and Wilms tumor." (PMID 33430133, 2021). "Dis3L2 was first identified in the causal mapping of Perlman syndrome, characterized by cellular over-growth, and is also implicated in Wilms tumor." (PMID 31909711, 2020). "Loss of function mutations in DIS3L2 have been shown to result in the congenital overgrowth condition Perlman syndrome in addition to a kidney tumour named Wilms’ tumour." (PMID 33370287, 2020). "DIS3L2 loss of function mutations have been implicated Perlman Syndrome and Wilms’ tumour of the kidney." (PMID 33370287, 2020). "While mutations in DIS3L2 are associated with Perlman syndrome, the biological significance of impaired DMD is obscure and pathological RNAs have not been identified." (PMID 32457326, 2020). "Dis3L2 is a highly conserved 3’-5’ exoribonuclease which is mutated in the human overgrowth disorders Perlman syndrome and Wilms’ tumour of the kidney." (PMID 33370287, 2020). "Dis3l2, mutations in which cause the Perlman syndrome, is a member of a highly conserved family of exoribonucleases that degrade RNA in a 3′-5′ direction." (PMID 29557542, 2019). "Studies with DIS3L2 and its catalytically inactive variant in Perlman syndrome revealed that DIS3L2 recognizes uridylated ncRNAs in the cytoplasm and subsequently degrades them." (PMID 30057901, 2018). "In fact, three cases with 2q37 deletion syndrome were reported to be affected with WT [reviewed in 22] and, furthermore, DIS3L2 mutations have been described in Perlman’s syndrome patients." (PMID 30344923, 2018). "Subsequently, two DIS3L2 heterozygous missense changes were identified in sporadic Wilms tumor, a tumor highly associated Perlman syndrome." (PMID 30057901, 2018). "903–908) investigated the molecular mechanisms by which mutations in the gene encoding the RNA degradation component DIS3L2 lead to Perlman syndrome." (PMID 30068702, 2018). "The RNase II exonuclease DIS3L2, a gene whose germline mutation causes Perlman syndrome, has recently been implicated in the degradation of polyuridylated pre-let-7." (PMID 30057901, 2018). "In 2012, germline mutations in the DIS3L2 exonuclease was discovered by a team working on Perlman syndrome." (PMID 30057901, 2018). "Closest homologues of Sts5 include S. cerevisiae Ssd1, S. pombe Dis3L2, and the human exonuclease Dis3L2, which has been associated with diseases such as Perlman syndrome and Wilm’s tumor, as well as Rrp44/Dis3." (PMID 27474797, 2016). "The clinical importance of Dis3L2 is demonstrated by its association with Perlman syndrome and Wilms' tumor susceptibility." (PMID 27630034, 2016). "More recently, the germline mutations within the DIS3L2 gene were identified to cause Perlman syndrome, a congenital overgrowth syndrome that is predisposed to Wilms tumor." (PMID 24755370, 2014). "Recently, germline homozygous mutations in DIS3L2 have been associated with Perlman syndrome, a rare overgrowth and cancer susceptibility disorder." (PMID 23805197, 2013). "Further, mutations in another human homolog, Dis3L2, have been recently shown to cause the Perlman syndrome of overgrowth and Wilms tumor susceptibility in the germline." (PMID 22853036, 2012). "Perlman syndrome (OMIM #267000) is an autosomal recessive condition caused by DIS3L2 mutations." (PMID 37065762, 2023). "DIS3L2 is associated with Perlman syndrome (#267000), an autosomal recessive disorder." (PMID 33772059, 2021).
Perlman syndrome (continued). "Whilst Perlman syndrome patients show a high predisposition to Wilms’ tumour, up to 30% of sporadic Wilms’ tumours were also shown to contain partial or complete deletion of DIS3L2." (PMID 33370287, 2020). "In addition, DIS3L2 has reportedly been associated with the Perlman syndrome, which is characterized by overweight in humans." (PMID 30687385, 2018). "In addition, Perlman syndrome and potentially a subset of Wilms tumors are caused by mutations in DIS3L2, a 3′ → 5′ exonuclease that is responsible for degrading numerous polyuridylated RNA substrates." (PMID 30057901, 2018). "The 2q37 chromosomal region and the DIS3L2 and miR-562 genes therein mapped had been already identified as associated with WT development in two congenital syndromic conditions, the 2q37 deletion syndrome and the Perlman syndrome." (PMID 30344923, 2018). "Interestingly, Dis3l2, which plays an important role in the Lin28a/let-7a pathway, is frequently mutated in Wilms’ tumor and causes the Perlman syndrome of overgrowth." (PMID 27881476, 2017). "Loss‐of‐function germline mutations in the DIS3L2 gene lead to the Perlman syndrome." (PMID 27647875, 2016). "Mutations in DIS3L2 have been associated with Perlman syndrome and with Wilms tumor susceptibility." (PMID 27647875, 2016). "Also, the precise defects that leads to Perlman syndrome is unclear as one can envision that disease is caused by the toxic accumulation of defective RNA species and/or by loss of specific RNA(s) that require DIS3L2 activity for function." (PMID 30057901, 2018). "DIS3L2 alterations were detected in 2 families (3 patients) and in 2 patients with Perlman syndrome." (PMID 40340749, 2025). "DIS3L2 gene also along with extreme π ratio and XP-EHH, encodes an exoribonuclease, and its germline mutations caused the Perlman syndrome with kidney abnormalities." (PMID 38355434, 2024). "Here, we present a case with the classic clinical features of Perlman syndrome and a DIS3L2 gene deletion that was discovered prenatally." (PMID 38161545, 2023). "A case of homozygous deletion of DIS3L2 exon 9 in a Japanese patient with Perlman syndrome was described later." (PMID 30057901, 2018). "Therefore, an abnormal activity of DIS3L2 is expected to participate in the etiology of several human disorders, as seen for the first time in the Perlman syndrome." (PMID 37340282, 2023). "Alternatively, given that Perlman Syndrome and Wilms’ tumour are early, developmental diseases is could be that DIS3L2 is essential to maintain proliferation early in development." (PMID 33370287, 2020). "DIS3L2 has been associated with human diseases such as Perlman syndrome and Wilm’s tumor, but a role in pulmonary diseases has not been described." (PMID 30390659, 2018). "Therefore, it appears that there is a level of tissue specificity in the activity of Dis3L2, which would be consistent with the phenotypes of Perlman syndrome specifically affecting overgrowth of specific organs such as the liver and kidney." (PMID 27630034, 2016). "In addition, in common with the effect of Dis3L2 in human diseases such as Perlman syndrome, our data show that Dis3L2 has specific effects on certain tissues as ubiquitous knockdown affects wing size but does not increase the mass of the whole fly." (PMID 27630034, 2016). "Therefore, the inactivation of DIS3L2, as reported in Perlman syndrome and in a subset of Wilms tumors, would have entirely different functional consequences for the cell, when compared with the effect of DIS3." (PMID 25925570, 2015).
Wilms tumor (20 papers, 2012 to 2025). An embryonal neoplasm characterized by the presence of epithelial, mesenchymal, and blastema components. "One of the Wilms tumor-associated genes, DIS3L2 (chr2:232,826,293-233,208,678), was located outside of the proximal breakpoint of our case (chr2: 234,275,216-234,264,038)." (PMID 24755370, 2014). "Given the association between DIS3L2 and the kidney tumour, Wilms’ Tumour, we tested whether the loss of DIS3L2 was sufficient to promote proliferation in HEK-293T cells, which are a more physiologically relevant, embryonic kidney derived cell line." (PMID 33370287, 2020). "Partial or complete DIS3L2 deficiency might cause an increased incidence of sporadic Wilms’ tumor." (PMID 33777092, 2021). "RNA-seq analysis over DIS3L2-null nephron progenitor cells from mouse, which serves as model for Wilms tumor research, revealed another DIS3L2 target, the insulin growth factor 2 (IGF2) that has been reported as an oncogene driving Wilms tumorigenesis." (PMID 37340282, 2023). "Dis3L2 is also likely to be important in sporadic Wilms' tumor as 30% of these tumors (6/20) show partial or complete DIS3L2 deletion." (PMID 27630034, 2016). "Moreover, mutations in typical Wilms tumour genes were identified, such as WT1, DIS3L2, WTX, CTNNB1 and the miRNA-processing genes DROSHA, DGCR8 and DICER1." (PMID 32161258, 2020). "Hence, to bypass lethality and further investigate the propensity of the Dis3l2 mutant animals to form Wilms tumors, the investigators crossed a floxed Dis3l2 line with a Wt1cre line." (PMID 30068702, 2018). "The resulting mutant animals in this case survived to adulthood but did not exhibit overgrowth or Wilms tumor, indicating that loss of Dis3l2 alone is not sufficient for the tumor formation." (PMID 30068702, 2018).
hepatocellular carcinoma (3 papers, 2021 to 2023). A malignant tumor that arises from hepatocytes. "Consistently, similar results were found in invasive human hepatocellular carcinoma cells, in which silencing of DIS3L2 by siRNA treatment inhibited cell proliferation." (PMID 37340282, 2023). "Another important study documented a pro-tumorigenic role for DIS3L2 in human hepatocellular carcinoma, via regulation of alternative splicing." (PMID 37340282, 2023). "Dis3L2 was found to be highly expressed in hepatocellular carcinoma tissues and promoted alternative splicing of the Rac1 gene through a nuclease-independent mechanism." (PMID 36823385, 2023). "DIS3L2 promotes hepatocellular carcinoma progression via the regulation of hnRNP U-mediated alterative splicing." (PMID 33777092, 2021).
colorectal cancer (2 papers, 2020 to 2023). A primary or metastatic malignant neoplasm that affects the colon or rectum. "In summary, this study demonstrates that DIS3L2 is overexpressed in colorectal cancer tissues and higher gene expression is associated with more advanced disease and worse patient prognosis." (PMID 37340282, 2023). "On the other hand, analysis of downregulated transcripts after knockdown of DIS3L2 showed enrichment in pathways associated with multiple types of cancers, namely “colorectal cancer”, including “regulation of actin cytoskeleton” and “mTOR signaling pathway”." (PMID 37340282, 2023). "In this work, we unveil that proper DIS3L2 expression is crucial for colorectal cancer (CRC) cells to maintain key tumorigenic properties." (PMID 37340282, 2023). "Next, we decided to analyze the prognostic value of DIS3L2 in patients with colorectal cancer using RNA-seq and clinical data from TCGA database." (PMID 37340282, 2023). "To do so, we performed a high-throughput RNA-sequencing experiment in colorectal cancer SW480 cells depleted from DIS3L2 or DIS3L2 + TUTs, by siRNA treatment." (PMID 37340282, 2023). "In the present study, we characterize the role of DIS3L2 in human colorectal cancer (CRC)." (PMID 37340282, 2023). "We observed that DIS3L2 was significantly overexpressed in colorectal cancer tissues compared to non-tumorigenic tissues (p < 0.001)." (PMID 37340282, 2023).
Infertility (2 papers, 2020 to 2024). "In female mice, Dis3l2-deficient oocytes fail to resume meiosis, resulting in arrest at the germinal vesicle stage and complete infertility." (PMID 39310107, 2024). "Furthermore, recent studies have delved into the role of DIS3L2 in female reproduction, revealing that Dis3l2-deficient oocytes nearly arrest at the germinal vesicle stage, resulting in total infertility in female mice." (PMID 39310107, 2024). "We further confirmed the specificity of the infertility phenotype in male flies where dis3L2 had been ubiquitously knocked down using Tubulin-GAL4 and UAS-dis3L2RNAi." (PMID 33370287, 2020).
anemia (1 paper, 2025). A reduction in the number of red blood cells, the amount of hemoglobin, and/or the volume of packed red blood cells. "Whole-body Zcchc6/Dis3l2 KO mice exhibit reticulocytosis and anemia." (PMID 40313744, 2025).
childhood cancer (1 paper, 2024).
hemoglobinopathies (1 paper, 2025). "Our findings reveal a conserved role for the ZCCHC6/DIS3L2 RNA editors in terminal erythropoiesis and demonstrate a post-transcriptional mechanism for γ-globin gene switching, advancing research into in vitro erythrocyte generation and γ-globin stabilization to ameliorate hemoglobinopathies." (PMID 40313744, 2025).
hip fracture (1 paper, 2025). Traumatic or pathological injury to the hip in which the continuity of either the femoral head, femoral neck, intertrochanteric or subtrochanteric regions is broken. "DIS3L2 was implicated by MAGMA at this locus although colocalisation analyses showed little evidence of shared HSM2 and hip fracture GWAS signals." (PMID 39574169, 2025).
liver cancer (1 paper, 2023). An epithelial or non-epithelial malignant neoplasm that arises from the liver. "This correlation observed in liver cancer together with the prognostic value of DIS3L2 in the advance stages of CRC suggest a potential role of this ribonuclease in tumor progression." (PMID 37340282, 2023).
male infertility (1 paper, 2024). The inability of the male to effect fertilization of an ovum after a specified period of unprotected intercourse. "Taken together, these findings underscore the essential role of DIS3L2 in mouse spermatogenesis, with its ablation resulting in dramatic loss of spermatogenic cells and subsequent male infertility." (PMID 39310107, 2024). "In meiotic spermatocytes, loss of DIS3L2 results in disturbed RNA metabolism, abnormal translation, and disrupted meiotic genes that perturb meiotic progression and induce cell apoptosis, leading to subsequent failure of spermatogenesis and male infertility." (PMID 39310107, 2024).
osteosarcoma (1 paper, 2020). A usually aggressive malignant bone-forming mesenchymal neoplasm, predominantly affecting adolescents and young adults. "The role of DIS3L2 in human cells was also shown to have some specificity since the overgrowth phenotype is not observed in following DIS3L2 knockdown in the osteosarcoma cell line U-2 OS." (PMID 33370287, 2020). "As this activation of mTORC is often independent of upstream signalling, including PI3-K, this could provide an explanation for the lack of influence of DIS3L2 on proliferation in osteosarcoma cells." (PMID 33370287, 2020). "Interestingly, the hyperplasia resulting from DIS3L2 depletion has some tissue specificity as the same experiments in the osteosarcoma cell line U-2 OS showed no phenotype." (PMID 33370287, 2020).
pyrexia (1 paper, 2016). "However, pyrexia and CG2678 show a clear regulation at the post-transcriptional level as the expression of pre-pyx and pre-CG2678 do not change significantly in dis3L2 knockdown discs compared to controls, but increase in expression by 2.4 and 2.1-fold respectively at the mRNA level." (PMID 27630034, 2016).
sarcoma (1 paper, 2025). A usually aggressive malignant neoplasm of the soft tissue or bone. "Our study, in addition to known PGVs in sarcomas, also showed two unusual PGVs that are not, including DIS3L2 deletion and NBN deletion." (PMID 40243416, 2025).
testicular tumor (1 paper, 2014). "DIS3L2 was therefore unlikely to cause the testicular tumor in this case, although it cannot be completely excluded that the DIS3L2 gene expression was deregulated in the affected tissue." (PMID 24755370, 2014).
viral infections (1 paper, 2016). "Uridylation and DIS3L2 were previously implicated in the rapid mRNA turnover in response to various stresses, such as viral infections or apoptosis." (PMID 27647875, 2016). "Upon viral infection, TUTase and DIS3L2 are involved in template‐dependent miRNA degradation (TDMD) and in the decay of improperly processed ncRNAs." (PMID 27647875, 2016).